INS (insulin)
Diseases named in the same sentence as INS in open-access papers (continued):
Sharing a sentence is not in itself a finding about the gene and the disease.
heart failure (continued). "Three of the genes associated with heart failure had treatment cASE: FAM241A in five conditions (copper, dexamethasone, insulin, caffeine, and vitamin A); BAG3 in five conditions (dexamethasone, caffeine, vitamin A, nicotine, and aldosterone); and KLHL3 in triclosan." (PMID 33988505, 2021). "Antihyperglycemic drugs that signal through insulin may further suppress autophagy and worsen heart failure." (PMID 32404204, 2020). "Even in subjects without heart failure, myocardial infarction, and diabetes mellitus, fasting plasma insulin level was positively associated with adverse echocardiographic features, which predispose them to a risk of heart failure." (PMID 31941015, 2020). "We used Mendelian randomization in 392,010 white British from the UK Biobank to assess the sex-specific role of genetically predicted insulin in myocardial infarction (MI) (14,442 cases, 77% men), angina (21,939 cases, 65% men) and heart failure (5537 cases, 71% men)." (PMID 31508506, 2019). "SGLT2i was significantly superior to INS (OR: 0.75, 95% CI 0.62–0.91), DPP4i (OR: 0.68, 95% CI 0.59–0.78), GLP1a (OR: 0.65, 95% CI 0.54–0.78), and TZD (OR: 0.46, 95% CI 0.27–0.77) in terms of heart failure risk." (PMID 30961600, 2019). "Therefore, situations of neurohumoral activation and of obesity/insulin-resistance converge in promoting cardiac GRK2 upregulation, which emerges as a potential factor linking insulin-resistant pathological conditions and heart failure." (PMID 30837878, 2019). "Interestingly, despite IL-13 gene tended to be upregulated, the IL-13 receptor subunit alpha 1 (IL-13Rα1) production was significantly decreased in the same cardiac muscle specimens of T2D patients with heart failure, who are by definition insulin-resistant." (PMID 29675435, 2018). "As result, an increased cardiac insulin resistance in heart failure may contribute to maintaining fatty acid oxidation rates." (PMID 29928647, 2018). "Treatment with trimetazidine in heart failure patients with idiopathic dilated cardiomyopathy shows a decrease in myocardial fatty acid oxidation rates, as well as improved left ventricular function and insulin sensitivity." (PMID 29928647, 2018). "As discussed, in heart failure a marked cardiac insulin resistance occurs." (PMID 29928647, 2018). "However, the specific mechanisms of high FFA levels in the pathophysiology of heart failure in insulin-resistant states are remain largely unclear." (PMID 30089498, 2018). "Insulin-induced inhibition of fatty acid oxidation is impaired in the failing heart leading to an increase in fatty acid contribution to the total ATP production, despite being inefficient substrate during heart failure." (PMID 29928647, 2018). "Insulin injections, along with the use of other drugs like TZDs, can precipitate cardiac failure." (PMID 28167928, 2017). "Prescribers provided insufficient water to patients with hyperosmolar dehydration, failed to anticipate falls in serum potassium in fasting diabetic patients on insulin infusions, and prescribed volume-expanding fluids for patients with a diagnosis of heart failure on admission." (PMID 29119469, 2017). "For people treated with insulin in combination with metformin, metformin therapy may be withdrawn in people developing contraindications to metformin therapy—for example, heart failure and renal impairment—leading to censorship." (PMID 27152598, 2016). "Hence, further research must be focused on detailed mechanisms that regulate the cardiovascular actions of insulin in other states, such as hypertension and heart failure." (PMID 27014078, 2016). "Indeed, insulin infusion has long been known to be effective in the treatment of patients with heart failure or undergoing coronary bypass surgery, although its cardioprotective mechanisms have not been elucidated." (PMID 25101057, 2014).
heart failure (continued). "Furthermore, a study conducted in Denmark prospectively followed 10,920 patients hospitalized for the first time for heart failure in 1997–2006 and who were receiving metformin, SU and/or insulin." (PMID 23574917, 2013). "Indeed, studies have highlighted the role of leptin and insulin in the elongation of cardiac myocytes, ventricular hypertrophy, and heart failure." (PMID 23468899, 2013). "Improving VO2peak and insulin sensitivity through exercise training could also improve CFR as has been shown in a recent study of heart failure patients." (PMID 22889317, 2012). "Furthermore, the activation of the RAAS occurring in patients with heart failure increases myocardial insulin resistance." (PMID 21933140, 2011). "Therefore, the acceleration of the glucose metabolism, along with the restoration of insulin sensitivity, would be the ideal metabolic therapy for heart failure." (PMID 21933140, 2011). "Thus, drugs that enhance insulin sensitivity, myocardial glucose uptake or both have been proposed as potential therapies in heart failure." (PMID 21359201, 2011). "Moreover, elevated plasma FFA levels, which are commonly present in heart failure, impair insulin signaling." (PMID 21933140, 2011). "Therefore, the ideal metabolic therapy for heart failure would be to induce glucose metabolism, together with the improvement of insulin sensitivity, while simultaneously blocking FFA uptake and FAO." (PMID 21933140, 2011). "In contrast, other groups have shown that Akt activity is not elevated in heart failure, or is actually decreased in advanced heart failure due to the disturbed signal transduction of the upstream effectors, including the insulin/IGF-1 receptor, through the IRS-1-PI3K pathway." (PMID 21933140, 2011). "The largest cluster (red) contained 199 keywords, including myocardial infarction, heart failure, mitochondrial-function, activated protein-kinase, energy-metabolism, skeletal-muscle, nitric-oxide synthase, endoplasmic-reticulum stress, gene-expression, insulin-resistance, and cardiomyopathy." (PMID 40693226, 2025). "Therefore, insulin and glucose infusion may be effective even in diabetic patients with heart failure who cannot discontinue SGLT2is at least 3 days preoperatively." (PMID 40855351, 2025). "In addition, a meta-analysis study also showed that insulin therapy did not affect cardiovascular events, heart failure, and mortality risk in these patients." (PMID 38243951, 2024). "Body weight and fasting plasma glucose and insulin were lower in the dapagliflozin-treated groups compared with vehicle controls; dapagliflozin treatment also markedly increased fasting plasma NEFAs and circulating βOHB levels in sham-surgery and heart-failure rats, indicative of SGLT2 inhibition." (PMID 39680452, 2024). "Moreover, myocardial insulin signaling is also compromised in heart failure." (PMID 39026321, 2024). "For instance, insulin sensitizers may lead to heart failure and weight gain, insulin secretagogues may cause excessive insulin secretion and damage to pancreatic beta cells, and alpha-glucosidase inhibitors may result in diarrhea and gastrointestinal discomfort." (PMID 38053837, 2023). "However, evidence regarding the effects of insulin on heart failure is conflicting." (PMID 34097240, 2022). "At this stage, the implantation of an LVAD and its contribution to the regulation of the neuromodulatory effects of insulin on the heart is pivotal and may decelerate, stabilize, or even revert the deleterious cascades that have been activated in end-stage heart failure." (PMID 35454166, 2022). "The result of this paper suggested that insulin therapy was harmful, especially in patients with low HbA1c levels or more severe forms of heart failure; therefore, specific management strategies and blood sugar targets may be needed when using insulin in patients with HF." (PMID 34496864, 2021).
heart failure (continued). "On the other hand, insulin use was also associated with greater utilization of SGLT2 inhibitors and GLP-1 receptor agonists which might be expected to reduce risk of recurrent MACE and heart failure events." (PMID 34158057, 2021). "Given that Mapk7-cko mice exhibited impaired cardiac insulin sensitivity and cardiac function 1 week post-MI, we explored further evidence on whether MAPK7 restoration could slow down the progression of cardiac insulin resistance and heart failure in Mapk7-cko hearts stressed with ischemia." (PMID 32223896, 2020). "In human heart failure, however, circulating plasma free fatty acids are elevated, secondary to increased sympathetic activation and—alongside a decreased capacity for fatty acid oxidation—can result in intramyocardial lipid accumulation and myocardial insulin resistance." (PMID 27528626, 2016). "However, it might also decrease myocardial insulin signaling, representing a potential mechanism for the beneficial effect of high-fat diets that decrease heart failure in rodent models of pressure overload or post-myocardial infarction." (PMID 28036029, 2016). "A heart failure does not appear to increase the risk for heart failure, whether insulin use specifically reduces the risk for heart failure is not known." (PMID 22957272, 2012). "Insulin was the treatment of choice for those with cardiovascular and renal comorbidities, including atherosclerotic cardiovascular disease (ASCVD), heart failure, and impaired kidney function." (PMID 38243951, 2024). "While insulin DPP-4 and/or metformin can be useful for additional glycemic control and thiazolidinediones must be avoided in heart failure stages B, C and D." (PMID 39835266, 2024). "It has been shown that the insulin signaling pathway is inactivated during the development of heart failure, and MAP2K1 is a key downstream gene of the insulin signaling pathway." (PMID 37234159, 2023). "Other medication classes, including DPP-4 inhibitors; insulin (glargine); alpha-glucosidase inhibitors; glinides; D2-dopamine agonists; GLP-1 agonist; and sulfonylurea are neutral to heart failure outcomes." (PMID 34926000, 2021). "Other drugs which are commonly used prior to use of basal insulin include SGLT‐2 inhibitors and GLP‐1 RAs,68,69 particularly in patients with CVD, heart failure, or chronic kidney disease." (PMID 33098260, 2021). "By comparative analysis, our results provide the changed expression profiling of metabolism signaling pathway, insulin signaling pathway, transcription factors MYC and C/EBPβ in the development of heart failure." (PMID 32460775, 2020). "Our results suggested that metabolism pathways and insulin signaling pathway, transcription factors MYC and C/EBPβ played critical roles in heart failure developmental progress." (PMID 32460775, 2020). "Metabolism signaling pathway, insulin signaling pathway, transcription factors MYC and C/EBPβ were inhibited in heart failure developmental progress." (PMID 32460775, 2020). "NPs play central roles in regulation of heart failure (HF), and are inactivated through not only NP receptor-C, but also neutral endopeptidase (NEP), dipeptidyl peptidase-4 and insulin degrading enzyme." (PMID 29344085, 2018). "Insulin and IGF effectors have been shown to enhance mitochondrial metabolism and be cardioprotective in the setting of cardiac failure." (PMID 27034963, 2016). "Two studies found a correlation between insulin sensitivity measured by the hyperinsulinemic-euglycemic clamp technique and CFR in heart failure patients (n = 39) and in obese subjects (n = 36 ), respectively." (PMID 26613591, 2015). "Observations in vitro and in heart failure patients suggest that atrial natriuretic peptide (ANP) promotes adiponectin release, an adipokine with insulin sensitizing properties." (PMID 22916229, 2012). "She exhibited no signs of heart failure, liver disease, renal impairment, or allergic reaction to insulin." (PMID 41476905, 2026).
heart failure (continued). "Increased GRK2 in heart failure (HF) initially may be protective but ultimately leads to maladaptive effects such as GPCR desensitization, insulin resistance, and apoptosis." (PMID 39960030, 2025). "Furthermore, the diet improves insulin sensitivity and lipid metabolism, addressing the impaired glucose and lipid handling observed in EAT of heart failure patients, which exacerbates cardiac stress." (PMID 39860003, 2025). "The use of ln (100 × UACR) demonstrated a higher predictive capacity for MACEs in patients with T2DM without a previous medical history of CVD, heart failure, or insulin use." (PMID 37922304, 2024). "According to the standard therapy for DKA, he was treated with continuous intravenous insulin infusion therapy, which unexpectedly resulted in an abrupt and transient elevation in blood lactate levels without exacerbation of heart failure and kidney function." (PMID 37139126, 2023). "Activin A produced by epicardial adipose tissue (EAT) T2D inhibits insulin action by inducing miR-143 in cardiomyocytes via the insulin regulator oxysterol-binding protein-related protein 8 (ORP8) to inhibit the Akt pathway, thereby slowing the progression of cardiac insufficiency." (PMID 36871006, 2023). "A relation between the muscle functional capacity and insulin resistance in heart failure has been shown previously and was not part of the current study protocol." (PMID 36547453, 2022). "Currently, there was lack of credible study reported the utility of cardiovascular complications (such as myocardial infarction, angina and heart failure) in T2DM patients who did not use insulin in China." (PMID 35910934, 2022). "Popular research topics in this field are specific diseases, such as acute coronary syndrome and heart failure; pathogenesis related to ACE2, insulin resistance and pericyte; the specific therapeutic drug chloroquine; and clinical characteristics, physical activity, and mental health." (PMID 36568760, 2022). "Other open questions include whether the insulin-PKB/AKT-SPEG-SERCA2a-Thr484 axis and Furin contribute more broadly to the pathogenesis of heart failure." (PMID 37583938, 2022). "Lastly, the difference in the prognosis between the patients with and without insulin was tested according to the severity of heart failure classified using the NYHA class and natriuretic peptide level." (PMID 34496864, 2021). "While MCD inhibitors have not been tested in patients with heart failure, preclinical studies have demonstrated that inhibition of MCD causes a decrease in fatty acid β-oxidation, increases glucose oxidation, and enhances insulin sensitivity." (PMID 34831481, 2021). "Accordingly, this study aimed to investigate the effect of carvedilol versus nebivolol on insulin resistance among non-diabetic, non-ischemic cardiomyopathy with heart failure." (PMID 32990863, 2020). "So, this study aimed to assess the effect of two of the third-generation B-blockers (carvedilol versus nebivolol) on insulin sensitivity state in non-diabetic patients with non-ischemic cardiomyopathy with heart failure." (PMID 32990863, 2020). "Furthermore, the insulin tolerance test (ITT) is inconvenient in younger children, and in patients with a history of seizure or cardiac insufficiency." (PMID 32431136, 2020). "Concern regarding potentially untoward effects of glycemic control arose from epidemiological evidence of increased mortality in insulin-treated vs. untreated T2DM patients, together with observations of insulin effects on cardiac events and mortality in heart failure complicated by T2DM." (PMID 29202762, 2017). "The prospective cohort study, enrolling 882 patients with one year follow-up, found that two patients (2/438) in the basal insulin had heart failure events and no patients (0/444) in exenatide group." (PMID 27169565, 2016).
heart failure (continued). "In this work, we demonstrate a similar requirement for the insulin pathway: in the presence of high dietary sugar, reduced activity of the IRS ortholog chico led to a decrease in fractional shortening that in turn contributed to progressive heart failure." (PMID 23326243, 2013). "Likewise, the activation of the insulin/IGF-1 cascade preserves mitochondrial energy metabolism, which in turn counteracts cardiotoxic oxidative stress and promotes survival in heart failure." (PMID 21933140, 2011). "Additionally, a more pronounced association between the UACR and MACEs was found in participants without insulin use or a previous history of CVD or heart failure." (PMID 37922304, 2024). "Three qualified MDDTs, 1) Insulin Dosing Systems: Perceptions, Ideas, Reflections and Expectations (INSPIRE) Questionnaire, 2) Kansas City Cardiomyopathy Questionnaire (KCCQ), and 3) Minnesota Living with Heart Failure Questionnaire (MLHFQ), were all present in the dataset after their qualification." (PMID 35441987, 2022). "Indeed, a study in which humans without heart failure were acutely administered sacubitril/valsartan showed that glucose and insulin levels were unchanged." (PMID 35733766, 2022). "However, adjustment for all of these variables and demographic characteristics did not diminish the strength of association of insulin treatment with risk of MACE and hospitalization for heart failure." (PMID 34158057, 2021). "RNA-seq data indicated distorted cardiac glucose pathways from non-infarct area of the failing hearts suffering from prolonged non-reperfused hypoxia, supporting the concept that cardiac insulin resistance contributes to the onset and development of heart failure in ischemic circumstances." (PMID 32223896, 2020). "Since heart failure is characterized by an increase in acetylation, the failing heart's hyperacetylated state could be potentiating leucine to ketone-mediated GLUT 4 inhibition and partially conferring insulin resistance." (PMID 29928647, 2018). "However, some studies reported the possible effects of multiple insulin- or noninsulin-therapies on glycemic control and heart failure." (PMID 30447687, 2018). "An alternative explanation could be that patients with symptoms that indicated cardiovascular disease or heart failure were prescribed insulin rather than glitazones or gliptins before subsequently having a diagnosis of these conditions." (PMID 27413012, 2016). "It is unknown whether changes in circulating glucose levels due to short-term insulin discontinuation affect left ventricular contractile function in type 2 diabetic patients with (T2D-HF) and without (T2D-nonHF) heart failure." (PMID 23308171, 2013). "In heart failure patients with DCM, there is myocardial insulin insensitivity so that glucose is not used as fuel." (PMID 31935874, 2020).